MTOR (mechanistic target of rapamycin kinase)
Diseases named in the same sentence as MTOR in open-access papers (continued):
Sharing a sentence is not in itself a finding about the gene and the disease.
diabetes (continued). "The mTOR pathway is the foremost multifunctional orchestrator of NAFLD/NASH progression and associated HCC development responding to metabolic syndrome, diabetes, hyperinsulinemia, insulin resistance, and dyslipidemia." (PMID 37760534, 2023). "As a master regulator, mTOR plays an important role in cardioprotection, diabetes and cellular metabolism, apoptosis, autophagy, mitochondrial biogenesis, nutrient sensing, and cardiac aging." (PMID 38132140, 2023). "TXNIP inhibition suppressed diabetes induced autophagy and activation of the mTOR signaling pathway." (PMID 37144033, 2023). "mTOR is a crucial regulator of cellular metabolism and catabolism, while the deregulation of mTOR signaling can induce many human diseases, including diabetes, degenerative disorders and cancer." (PMID 37755297, 2023). "Increased expression of mTOR in diabetes is known to result in insulin resistance, which has brought about the creation of mTOR inhibitors such as rapamycin for diabetic treatment." (PMID 38114067, 2023). "Leukocyte cell-derived chemotaxin 2 (an antiangiogenic factor) increases the level of endothelial tight junction proteins by activating the Tie2/AKT/mTOR signaling pathway and can improve BRB damage associated with diabetes." (PMID 37978169, 2023). "The deregulated activity of mTOR is involved in many pathophysiological conditions, such as ageing, Alzheimer's disease, diabetes, obesity and cancer." (PMID 37551845, 2023). "Among these signaling pathways, AMPK/mTOR and Nrf2/Keap1 are the principal ones that Sestrin2 is suggested to be involved in the pathogenesis of diabetes and diabetic complications." (PMID 37920252, 2023). "The AMPK suppresses the activity of the mammalian target of the Rapamycin Kinase (mTOR) pathway thus slowing down disease progression as mTOR is thought to take part in the metabolic syndrome and diabetes progression." (PMID 37893528, 2023). "This is of paramount importance given the great potential of stem cell therapy and the implication of mTOR signaling in a variety of diseases, such as cancer, diabetes, cardiovascular diseases, neurodegenerative diseases, and skin and ocular diseases." (PMID 37139607, 2023). "Robust activation of mTOR (mammalian target of rapamycin) signaling in diabetes exacerbates myocardial injury following lethal ischemia due to accelerated cardiomyocyte death with cardiac remodeling and inflammatory responses." (PMID 37240345, 2023). "In diabetes, an over-nutritional condition, autophagy is suppressed through the activation of the mammalian target of rapamycin (mTOR) pathway, a nutrient-sensing pathway." (PMID 37109553, 2023). "By analyzing transcripts and protein activity of key components of the Keap1/Nrf2/HO-1 and AMPK/mTOR pathways, we further collected evidence of the mechanism by which oral polyphenol administration can significantly improve diabetes and its complications." (PMID 36832842, 2023). "Recent studies have determined that mTOR signaling pathways regulate high glucose-induced apoptosis in diabetes." (PMID 36820117, 2023). "The proteins in this network were related to some signaling pathways, such as mTOR signaling pathway, cellular senescence, hippo signaling pathway, and type 2 diabetes mellitus." (PMID 37828521, 2023). "An increase in the autophagy flux has been reported in podocytes in response to high glucose, and it is protective against diabetes-induced glomerulosclerosis, which is characterized by mTOR activation." (PMID 37569500, 2023). "More specifically, klotho regulates the upregulation of autophagic flux by inhibiting the AKT/mTOR pathway or the IGF-1-mediated PI3K/Akt/mTOR pathway to improve diabetes and kidney injury." (PMID 37143722, 2023). "In overfeeding conditions with a surplus of nutrient and hormonal signals, the mTOR pathway is overactivated, contributing to the pathogenesis and maintenance of many diseases, such as obesity, diabetes mellitus type 2, and metabolic syndrome." (PMID 36986146, 2023).
diabetes (continued). "Deregulation of mTOR-signaling network leads to various diseases such as cancer, diabetes and age-related disorders." (PMID 35001007, 2022). "Once diabetes develops, hyperglycemia creates a vicious circle of mTOR activation, inhibition of AMPK and deregulation of Akt pathway." (PMID 36476132, 2022). "Taken together, these results emphasized that the PI3K/Akt/mTOR/NF-κB p65 pathway, especially mTOR, played an important role in the mechanism by which food allergies affect diabetes." (PMID 36496564, 2022). "Taken together, since the increased mTOR signaling at the wound edge is positively correlated with wound epithelization, the deficiency of mTOR signlaing activity may represent one of the key factors preventing wound closure and eventual disturbed repair in diabetes mellitus." (PMID 35938153, 2022). "As the incidence of diabetes mellitus in TSC patients on mTOR inhibition is only 2.5% in 5 years, we think this should open the debate if regular screening is warranted in this population." (PMID 35804402, 2022). "Our results show that diabetes-induced mTOR activation contributes to TFEB dysfunction and therefore perturbs lysosomal homeostasis by impairing lysosomal biogenesis and clearance in TECs." (PMID 35082964, 2022). "In conclusion, diabetes-induced mTOR activation represses TFEB function, thereby perturbing lysosomal homeostasis through impairing lysosomal biogenesis and clearance in TECs." (PMID 35082964, 2022). "This is indicative for diabetes induced matrix remodeling and differentiation being mediated by mTOR signaling at this point." (PMID 36386326, 2022). "Many studies have demonstrated that the “mTOR signaling pathway” plays an important role in the pathophysiological process of diabetes." (PMID 35449001, 2022). "Dysregulation in mTOR signaling is involved in several diseases such as obesity, type 2 diabetes mellitus, cancer, and neurodegenerative disorders." (PMID 35528246, 2022). "mTOR inhibitors show promise in a range of health conditions including age-related diseases and those affecting patients with diabetes." (PMID 35388291, 2022). "Salidroside protects against diabetes-induced cardiac dysfunction by modulating the mechanistic target of rapamycin (mTOR), AMPK, and AKT/heme oxygenase-1(HO-1) signaling pathways." (PMID 35281941, 2022). "In a study on diabetes, it was found that the PI3K/Akt/mTOR signaling pathway is associated with the apoptosis of pancreatic β cells in Wistar rats with STZ-induced diabetes." (PMID 36496564, 2022). "Although hyperglycemia is a frequent side effect in other indications for mTOR inhibition, incidence of diabetes mellitus in TSC patients was only 2.5%." (PMID 35804402, 2022). "The AMPK/mTOR pathway is widely taken part in the development of numerous diseases, including ischemic acute kidney injury, diabetes, and cardiac dysfunction." (PMID 35291946, 2022). "The examination of translation in the kidney during diabetes has historically focused on mTOR/AMP kinase signaling." (PMID 35406730, 2022). "Drugs and natural products used to treat or alleviate diabetes can regulate autophagy through the mTOR, AMPK, ERK, and Hedgehog signaling pathways to exert a blood glucose-lowering effect." (PMID 36355132, 2022). "Overall, this study showed that hyperglycemia, hyperlipidemia, injury of the liver, oxidative stress, and suppression of the Akt/mTOR signaling pathway occur in streptozotocin-induced diabetes rats." (PMID 35528246, 2022). "Current evidence also shows that MTOR activation plays a crucial role in the pathogenesis of insulin resistance in type 2 diabetes mellitus (T2DM)." (PMID 36532549, 2022). "In particular, current researches declared that the regulation ATG1/ULK1 by mTOR and AMPK pathway were associated with kidney disease pathogenesis in diverse conditions, such as acute kidney disease (AKI) and diabetes mellitus." (PMID 36081940, 2022).
diabetes (continued). "Male sex, Caucasian race, pretransplant malignancy, hypertension- or diabetes-induced ESRD, retransplantation, diabetes history, deceased donor, cyclosporin, and mTOR inhibitor use were independent risk factors for posttransplant skin cancer mortality." (PMID 36505816, 2022). "As a potent and specific inhibitor of mTOR, rapamycin can be used to treat diabetes, advanced kidney cancer, and Huntington’s disease." (PMID 36451813, 2022). "The interruption of mTOR signaling results in several disorders including cancers, diabetes, obesity, and neurodegenerative diseases." (PMID 36590916, 2022). "The interpretation of LATS2 action in diabetes and apoptosis has been confronted with an explanation of the role and interaction of mTOR and autophages in these processes." (PMID 35054822, 2022). "Another module was associating with mTOR signaling and AMPK signaling pathways, which play important roles in the development of diabetes and DR." (PMID 34707685, 2021). "Many studies have reported relationships between mTOR and human diseases such as cancer, cardiovascular diseases, diabetes, obesity and neurological disorders, which are involved in age-related diseases and in lifespan regulation." (PMID 33809299, 2021). "Substantial researches revealed that AKT and mTOR played a central role in regulating many basic activities of cells including autophagy and AKT/mTOR dysregulation caused diseases like cancer and diabetes." (PMID 34031264, 2021). "At advanced stages of diabetes, we observed downregulation of the mTOR activity accompanying with autophagy activation and neuronal cell loss." (PMID 33637094, 2021). "Metformin, a clinically used AMPK agonist for diabetes, or rapamycin, a specific mTOR inhibitor, inhibits KOA synovial inflammation by increasing phosphorylation of AMPK or inhibiting phosphorylation of mTOR, respectively." (PMID 34876884, 2021). "The results demonstrated that activity of the mTOR pathway was initially increased at early period of diabetes and this increase was reversed by insulin-independent glycemic control." (PMID 33637094, 2021). "A key finding of this study is that the diabetes-induced increase in VEGF expression in the diabetic rat retina is inhibited by the mTOR inhibitor, rapamycin." (PMID 33479328, 2021). "Metformin, a classic hypoglycemic agent for diabetes mellitus, has recently been found to have anti-tumor activity by inhibiting mTOR in various tumors." (PMID 34659343, 2021). "Mechanism studies showed that exogenous H2S activated the AMPK/mTOR signaling pathway through increasing the p-AMPK/AMPK ratio and decreasing the p-mTOR/mTOR ratio in a diabetes model." (PMID 34201520, 2021). "Most importantly, both GYY4137 and AICAR stimulated AMPK phosphorylation and diminished mTOR phosphorylation in high glucose-challenged H9c2 cells, suggesting that H2S ameliorates diabetes-induced cardiac damage in an AMPK/mTOR pathway-dependent manner." (PMID 34764865, 2021). "Metformin, which is used to treat diabetes mellitus, also plays a role in negatively regulating mTOR activation by stimulating AMPK." (PMID 34950150, 2021). "Increased mTOR activity is common in most human diseases such as cancers, diabetes, and genetic disorders." (PMID 35178356, 2021). "The relationship between H2S-induced autophagy and the AMPK/mTOR signaling pathway needs further study in diabetes." (PMID 34201520, 2021). "Of note, the upregulation of mTOR activity followed by downregulation has been reported in the other tissues of STZ-induced diabetes models, but the follow-up period lasted only 6 weeks." (PMID 33637094, 2021). "At present, the mTOR gene has been found to play a role in a variety of diseases, such as neurological diseases, tumors, and diabetes." (PMID 34194607, 2021).
diabetes (continued). "Our preliminary study also uncovered that the simulated DD conditions caused mitophagy via GluR2/mTOR signal in hippocampal neurons, which implied the close connection between GluR2(glutamate AMPA receptor subunit) and diabetes‐related depression." (PMID 34213839, 2021). "Autophagy promoting agents, including mTOR inhibitors such as rapamycin, are regarded as a potential therapeutic strategy against cancer, diabetes, and neurodegenerative disorders." (PMID 33460487, 2021). "As previously reported, mTOR regulates lipid and glucose metabolism, thus playing a major role in metabolic diseases, such as obesity and diabetes mellitus type 2." (PMID 34066040, 2021). "At this point, we wondered that if autophagy dysregulation involved in diabetes-induced neurodegeneration, what is the role of the mechanistic target of rapamycin (mTOR) pathway in this context, which is the master regulator of autophagy." (PMID 33637094, 2021). "The mTOR/p70S6K signal pathway plays an important role in the regulation of cell proliferation, which involves in the pathological process of cancer, diabetes, cardiovascular disease, and so on." (PMID 33777154, 2021). "Recently, it has become obvious that mTOR dysregulation is involved in several age-related diseases, such as cancer, neurodegenerative diseases, and type 2 diabetes mellitus." (PMID 34309456, 2021). "The increased mTOR activity is related to insulin resistance, and short-term treatment with rapamycin can lead to an increase of insulin sensitivity, thus ameliorating diabetic mellitus." (PMID 33691762, 2021). "Previous studies showed that the mammalian target of rapamycin (mTOR) signaling pathway has an essential role in the pathogenesis of metabolic syndrome, obesity, and diabetes." (PMID 35178356, 2021). "Being a major node in the (PI3K/AKT/mTOR) pathway, we think that its disruption will result in hyperglycemia and diabetes." (PMID 34360895, 2021). "At present, a large number of studies have confirmed that the PI3K/Akt/mTOR signaling pathway is related to some complications of diabetes, such as diabetic nephropathy, neuropathy, and myocardial ischemia." (PMID 32689970, 2020). "FKBP11 is involved in the regulation of mTOR and the pathogenesis of stress-related inflammatory diseases, including type 2 diabetes mellitus, systemic lupus erythematosus, and hepatitis." (PMID 33425993, 2020). "During diabetes, hyperglycemia has been found to induce the overactivation of mTOR signaling in lysosomes." (PMID 32106480, 2020). "AMPK, an energy receptor, is a key regulatory site in endocrine diseases such as obesity and diabetes, and activates autophagy by inhibiting mTOR activity." (PMID 32082187, 2020). "Dysregulation of mTOR signaling pathway is proved to be involved in a variety of pathological process, including cancer, diabetes and neurodegeneration." (PMID 32922169, 2020). "Glomeruli from mice with podocyte-specific knockout of GLUT4 are protected from diabetes-induced hypertrophy, mesangial expansion and albuminuria, and fail to activate the mTOR pathway." (PMID 32340263, 2020). "During the course of type II diabetes, mTOR overactivation and hyperinsulinemia eventually lead to beta-cell exhaustion and insulin insufficiency, from pre-diabetes to diabetes." (PMID 32534452, 2020). "Our data indicate that diabetes increased mTOR and S6 phosphorylation in renal glomeruli of db/db mice as compared to non-diabetic littermate controls." (PMID 33303821, 2020). "The mechanistic Target of Rapamycin (mTOR) signaling pathway is a key sensor of cellular energy/nutrient abundance and stress and altered functions are involved in the pathophysiology of diabetes, cancer, and aging." (PMID 31248103, 2019). "Corticosteroids, anti-calcineurin, and mammalian target of rapamycin (mTOR) inhibitors have a major diabetogenic impact and greatly contribute to the increase in diabetes prevalence after transplantation." (PMID 31227028, 2019).
diabetes (continued). "The present study demonstrates a potential novel crosstalk in β-cells between FFAR1 and the Akt-mTOR pathway, a major signaling pathway involved in insulin regulation and diabetes." (PMID 31426858, 2019). "In the condition of diabetes, the cardio SIRT1 is a molecule directly or indirectly linked to the mTOR signaling pathway and autophagy." (PMID 31080547, 2019). "Newly identified classes of mTOR inhibitors are being developed to block autoimmune diseases and transplant rejections but also to treat obesity, diabetes, and different types of cancer." (PMID 30609721, 2019). "An emerging body of evidence has suggested that mTOR protein plays a key role in the development of diabetes." (PMID 30634545, 2019). "That would explain the puzzling observations that conversion to rapamycin resolved diabetes in 80% patients 91, and that conversion from calcineurin inhibitors to mTOR inhibitors stabilizes diabetic and hypertensive nephropathy after liver transplantation." (PMID 31406105, 2019). "It has been demonstrated that metformin, an agent used to control hyperglycemia in diabetes mellitus, inhibits mTOR activity and promotes autophagy and protects against endothelial cell senescence." (PMID 31080547, 2019). "Metformin activates AMPK signal pathway, which not only decreases insulin resistance in type 2 diabetes mellitus but also blocks AMPK-mediated mTOR activation even in cancer stem cells (CSCs)." (PMID 31164151, 2019). "On the other hand, the most significant enriched pathway for hsa-miR-4709-3p was mTOR signaling pathway, the role of which is well established in diabetes mellitus and its complications, including diabetic nephropathy." (PMID 31455266, 2019). "Hyperleptinemia can coexist with diabetes mellitus and has the ability to stimulate the activity of mTOR and promote the vascular smooth muscle cell proliferation." (PMID 31080547, 2019). "In different model systems of diabetes including of human origin, stress-induced nascent granule degradation (SINGD) contributes to loss of insulin along with mammalian/mechanistic Target of Rapamycin (mTOR)-dependent suppression of macroautophagy." (PMID 31346174, 2019). "It is known that a high level of free fatty acids leads to constitutive activation of mTOR signaling, a process related to the development of diseases such as diabetes and obesity." (PMID 30781653, 2019). "Further investigation is required to determine the relationship between the animal’s metabolic status and insulin-mTOR signaling, especially in pathophysiological states, such as obesity or diabetes." (PMID 31714935, 2019). "Therefore, chrysin may counteract diabetes-associated mesangial cell protrusion and migration through disturbing actin polymerization/bundling and focal adhesion formation by interfering with autophagy/mTOR activation." (PMID 30634545, 2019). "Although it has been well established that rapamycin is protective in atherosclerosis by inducing autophagy via inhibition of mTOR, the role of mTOR in diabetes mellitus is complex." (PMID 31080547, 2019). "In particular, the diabetes drug metformin has antiinflammatory effects and inhibits pathways such as mammalian target of rapamycin (mTOR) signaling, which are important in the host defense against Mycobacterium tuberculosis." (PMID 30753544, 2019). "Our unexpected discovery of the non-overlap impact of AMPK and mTOR signaling in the upper small intestine raises the possibility that targeting the mTOR-dependent pathway in the small intestine represents a unique strategy to lower glucose levels in diabetes." (PMID 30755615, 2019). "Modulation of mTOR function to increase autophagy and inhibit apoptosis is involved in the protective effects of pharmacologic agents targeting diabetes and Alzheimer’s disease (AD)." (PMID 30684442, 2019). "Multiple reports have provided evidence of mTOR dysregulation in a host of diseases, including diabetes, cancer, hypertrophy, and heart failure." (PMID 30405071, 2018).